CYP4X1 (cytochrome P450 family 4 subfamily X member 1)
Description:
A cytochrome P450 monooxygenase that selectively catalyzes the epoxidation of the last double bond of the arachidonoyl moiety of anandamide, potentially modulating endocannabinoid signaling. Has no hydroxylase activity toward various fatty acids, steroids and prostaglandins. Mechanistically, uses molecular oxygen inserting one oxygen atom into a substrate, and reducing the second into a water molecule, with two electrons provided by NADPH via cytochrome P450 reductase (CPR; NADPH-ferrihemoprotein reductase).
Synonyms: MGC40051; CYPIVX1
Tractability: Small molecule: it belongs to a druggable protein family. Antibody: UniProt predicts a signal peptide or a membrane-spanning region. PROTAC: ubiquitination databases record sites on it.
Target class: Cytochrome P450 family 4X; Cytochrome P450 family 4; Cytochrome P450; Cytochrome P450 4X1; Enzyme
Gene: Protein-coding gene on chromosome 1 (47,023,666 to 47,050,751, forward strand). Ensembl gene ENSG00000186377.
Subcellular location: Endoplasmic reticulum membrane; Microsome membrane
Gene Ontology:
Molecular function: anandamide 14,15 epoxidase activity; heme binding; iron ion binding; monooxygenase activity; oxidoreductase activity, acting on paired donors, with incorporation or reduction of molecular oxygen
Cellular component: endoplasmic reticulum membrane
Genetic constraint (gnomAD): Loss-of-function variants: 44 observed, 62.31 expected, observed/expected ratio (o/e) 0.71, 90% interval 0.55 to 0.91. The upper end of that interval is the gene's LOEUF score, 0.91, which puts it in group 3 of 6, group 1 being the genes least tolerant of losing a copy. Missense variants: 532 observed, 660.33 expected, observed/expected ratio (o/e) 0.81, 90% interval 0.75 to 0.87. Synonymous variants: 227 observed, 242.75 expected, observed/expected ratio (o/e) 0.94, 90% interval 0.84 to 1.04.
Homologues: Orthologues: chimpanzee CYP4X1 (99% identical), macaque CYP4X1 (94% identical), dog CYP4X1 (74% identical), rabbit CYP4X1 (73% identical), guinea pig CYP4X1 (73% identical), mouse Cyp4x1 (71% identical), rat Cyp4x1 (70% identical), tropical clawed frog cyp4b1.5 (47% identical), tropical clawed frog cyp4b1.2 (47% identical), tropical clawed frog XB5810926 (46% identical), zebrafish cyp4t8 (41% identical), Drosophila melanogaster Cyp4d2 (31% identical), and 28 more. Paralogues in human: CYP4Z1 (53% identical), CYP4A11 (48% identical), CYP4A22 (48% identical), CYP4B1 (46% identical), CYP4F11 (41% identical), CYP4F2 (41% identical), CYP4F12 (41% identical), CYP4F3 (41% identical), CYP4F8 (39% identical), CYP4F22 (39% identical), CYP4V2 (32% identical), CYP19A1 (20% identical).
Diseases named in the same sentence as CYP4X1 in open-access papers:
CYP4X1 is named in the same sentence as 27 diseases in open-access papers, as found by Europe PMC text mining. Sharing a sentence is not in itself a finding about the gene and the disease. The quoted sentences say what the papers report.
breast carcinoma (5 papers, 2017 to 2025). "According to other researchers, CYP4X1 protein expression is linked to increased tumor grade in breast cancer." (PMID 40076494, 2025). "Protein expression of CYP4X1 was associated with increasing tumor grade in tissue microarrays from 170 breast cancer patients detected by immunohistochemistry." (PMID 33802237, 2021). "In conclusion, the present study brings replicated association of variant rs17102977 in CYP4X1 with the response of patients to the neoadjuvant cytotoxic chemotherapy and warrants further research of genetic variation CYPs in breast cancer." (PMID 33802237, 2021). "Protein expression of CYP4X1 was already studied in breast cancer, but the role of its genetic variation is unexplored." (PMID 33802237, 2021). "High numbers of Cyp4x1 ESTs were also found in malignant tissues, pointing to a possible role in tumorigenesis, and using immunohistochemistry it was shown that Cyp4x1 showed high levels of expression in human breast cancer." (PMID 29227996, 2017). "The endocannabinoid system is involved in various physiological processes, including inflammation, immunomodulation, and suppression of different cancers, including breast cancer; thus, CYP4X1 may play a role in the response to anticancer chemotherapy via physiological processes." (PMID 41020804, 2025). "The others, such as CYP2W1, CYP2S1, CYP2U1, CYP4X1, and CYP4V2, are less specific, but their overexpression in breast cancer has also been found." (PMID 41020804, 2025).
colon cancer (3 papers, 2008 to 2025). "Statistical analysis of the UALCAN database data revealed that CYP4X1 expression was significantly higher in colon cancer tissues compared to normal tissues (p < 1 × 10−12)." (PMID 40076494, 2025). "Here, it is elucidated that CYP4X1/sEH-dependent endocannabinoid metabolism governs immune evasion in colon cancer by promoting the infiltration of regulatory T cells (Tregs) and impairing CD8+ T cell effector function." (PMID 41276938, 2025). "Moreover, CYP4X1 and sEH levels jointly predict prognosis and immune infiltration in human colon cancer." (PMID 41276938, 2025). "The cytochrome P450 CYP4X1 gene (monooxygenase activity, electron transport) increased in MG-thymoma compared to healthy thymuses, with higher thymus than colon expression and increases in colon cancer as well." (PMID 18545673, 2008). "Together, this study highlights that CYP4X1/sEH-dependent endocannabinoid metabolism controls CAF-mediated immune evasion, and targeting the CYP4X1/sEH-14,15-EET-EA-GPR119 axis represents a promising therapeutic strategy for improving anti-PD-1 therapy in colon cancer." (PMID 41276938, 2025).
gastric cancer (3 papers, 2021 to 2024). A primary or metastatic malignant neoplasm involving the stomach. "Recently, a lower gene expression of CYP4X1 was associated with shorter overall survival of Chinese gastric cancer patients treated with capecitabine and oxaliplatin." (PMID 33802237, 2021). "Gastric cancer patients with low expression of CYP4X1 receive less clinical benefit from capecitabine and cisplatin and have a worse survival prognosis." (PMID 38556542, 2024). "For RFS, high expression of OLFML2B, MT1M, and SIDT2 indicated a poor RFS of patients with GC, whereas gastric cancer patients with higher expression of CYP4X1 possessed better RFS from TCGA cohort." (PMID 36092901, 2022).
glioma (3 papers, 2020 to 2024). A benign or malignant brain and spinal cord tumor that arises from glial cells (astrocytes, oligodendrocytes, ependymal cells). "As for its correlations with GBM, recently, two successive related publications confirmed that CYP4X1 contributes to the inhibition of glioma angiogenesis." (PMID 33329750, 2020).
breast tumors (1 paper, 2025). "Although less specific, the other orphan CYPs, such as CYP2W1, CYP2S1, CYP2U1, and CYP4X1, exhibit significantly higher expression in breast tumors compared to normal tissues." (PMID 41020804, 2025).
colon adenocarcinoma (1 paper, 2025). "Based on various clinicopathological parameters, we analyzed the mRNA expression patterns of CYP4X1 in normal rectal tissues and colon adenocarcinoma (COAD)." (PMID 40076494, 2025). "The results show that CYP4X1 expression was significantly higher in colon adenocarcinoma (COAD) and rectal adenocarcinoma (READ) compared to normal tissues, as further confirmed through UALCAN analysis." (PMID 40076494, 2025).
colorectal cancer (1 paper, 2025). A primary or metastatic malignant neoplasm that affects the colon or rectum. "Kaplan–Meier analysis comparing the survival rates of colorectal cancer patients based on CYP4X1 expression revealed that patients with high CYP4X1 expression had shorter survival times than those with low CYP4X1 expression (log-rank test, p < 0.001)." (PMID 40076494, 2025). "We used shRNA to knock down CYP4X1 expression in HCT116 colorectal cancer cells (HCT116; 91.4% ± 2.8%, p < 0.001)." (PMID 40076494, 2025). "CYP4X1 mRNA expression was significantly downregulated in all colorectal cancer cell lines (p < 0.001)." (PMID 40076494, 2025). "This study focused on elucidating the role of CYP4X1 in colorectal cancer (CRC)." (PMID 40076494, 2025). "In addition, an in vivo analysis was conducted to elucidate the regulatory role of CYP4X1 in colorectal cancer tumorigenesis." (PMID 40076494, 2025).
Creutzfeldt-Jakob disease (1 paper, 2021). "Two SNPs in CYP4X1 were also associated with the early onset of Creutzfeldt-Jakob disease in Italian patients." (PMID 33802237, 2021).
hypospadias (1 paper, 2020). Hypospadias is the displacement of the urethral meatus on the ventrum of the penis. "We identified a significant causal effect of methylation at cg04714159 on hypospadias, as well as potential causal effects of multiple members of the cytochrome P450 family of enzymes in this region (CYP4A11, CYP4A22, CYP4B1, CYP4X1, CYP4Z2P)." (PMID 32728162, 2020).
morbid obesity (1 paper, 2017). An excess of body weight, normally defined as an individual with a body mass index greater than 35 or a body weight greater than one hundred percent of ideal body weight. "When the Cyp4x1-knock out mice were tested with glucose or insulin challenges at 20 weeks of age we found no significant impairment of glucose homeostasis, so the phenotype is one of increased adiposity rather than of morbid obesity." (PMID 29227996, 2017).
osteosarcoma (1 paper, 2023). A usually aggressive malignant bone-forming mesenchymal neoplasm, predominantly affecting adolescents and young adults. "In addition, both authors’ microarray analyses exhibited GSTP1 and CYP4X1 genes responsible for cell detoxification, a drug chemoresistance mechanism in osteosarcoma." (PMID 37107591, 2023).
ovarian carcinoma (1 paper, 2023). A malignant neoplasm originating from the surface ovarian epithelium. "The hypomethylated CYP4X1 and CYP4Z1 genes together are presumed to be involved in human breast and ovarian cancers." (PMID 38264209, 2023).
steatosis (1 paper, 2024). Increased lipid within the cytoplasm of cells. "In human patients, the CYP4F12, CYP4F22, and CYP4V2 mRNA levels increase in steatosis and MASH, while the levels of CYP4B1, CYP4X1, and CYPZ1 mRNAs decrease in steatosis and MASH while the mRNA for these genes increases in HCC." (PMID 40452921, 2024).
tumor (12 papers, 2010 to 2025). "Of the 50 or more P450 genes present on the array, only 19 had detectable expression levels in our tumour biopsies, and of these, only CYP4X1 had significant differential expression associated with chemotherapeutic response." (PMID 20551950, 2010). "The overexpression of CYP4X1 is closely associated with key factors such as TNM stage, tumor differentiation, depth of invasion, and lymph node metastasis, which influence CRC patient survival." (PMID 40076494, 2025). "And CYP4X1 high expression was strongly associated with advanced TNM stage, poor tumor differentiation, deeper invasion, and lymph node metastasis." (PMID 40076494, 2025). "Based on TCGA databases such as GENT2, UALCAN, and GEPIA, we analyzed CYP4X1 expression at the mRNA level in both tumor and normal tissues and investigated its correlation with patient survival." (PMID 40076494, 2025). "Furthermore, the tumor-forming ability in mice injected with cell lines where CYP4X1 expression was suppressed decreased." (PMID 40076494, 2025). "There are few studies on the role of CYP4X1 in tumour occurrence and development." (PMID 38556542, 2024). "However, the precise role of CYP4X1 and sEH in tumor immune evasion is poorly understood." (PMID 41276938, 2025). "The CYP4X1 KD HCT116 cells formed smaller tumor masses and exhibited slower tumor growth compared to the control cells (p < 0.001)." (PMID 40076494, 2025). "The results indicated that CYP4V2, CYP4X1, and CYP4Z1 expression were correlated with a higher tumor grade." (PMID 40723371, 2025). "A positive correlation with increasing tumour grade has been observed with the expression of CYP4V2, CYP4X1 and CYP4Z1; while CYP1B1, CYP3A5 and CYP51 were significantly associated with the ER status of the tumour." (PMID 33809117, 2021). "We report that the CYP genes with highest expression, ranked by the mean expression in tumor tissues for all patients, are: CYP1B1 (mean normalized expression 112.8), CYP4Z1 (92.2), CYP2A6 (75.7), CYP4X1 (65.1), CYP4B1 (31.5), CYP2A7 (30.8), and CYP4F8 (11.6)." (PMID 28684774, 2017). "The results showed that CYP4V2, CYP4X1, and CYP4Z1 expression correlated with a higher tumor grade." (PMID 40723371, 2025). "In our laboratory, protein-level analysis using immunohistochemical (IHC) staining of tissues from 243 CRC patients revealed that CYP4X1 expression was consistently increased across multiple clinicopathological factors, including TNM stage, tumor differentiation, depth of invasion, and metastasis." (PMID 40076494, 2025). "At the same time, CYP4V2, CYP4X1, and CYP4Z1 showed correlation with the tumor grade." (PMID 41020804, 2025). "CYP2S1, CYP2U1 and CYP4X1 exhibited the highest percentage of strong immunoreactivity in contrast to other isoforms such as CYP2J and CYP3A4, which displayed no reactivity in majority of the tumours." (PMID 33809117, 2021).
cancer (6 papers, 2015 to 2025). A tumor composed of atypical neoplastic, often pleomorphic cells that invade other tissues. "CYP4X1 is associated with cancer activity; its overexpression has been reported in breast, gastric, and brain cancers." (PMID 40076494, 2025). "Mechanistically, CYP4X1/sEH-derived 14,15-EET-EA upregulates PD-L1, CXCL12, and TGF-β in cancer-associated fibroblasts (CAFs) via the GPR119-Gs/β-arrestin 2 signaling axis." (PMID 41276938, 2025). "Using TCGA data, the GENT2, UALCAN, and GEPIA databases were employed to compare CYP4X1 expression in various cancer types and normal tissues." (PMID 40076494, 2025). "CYP4X1 plays a central role in neurovascular brain functions and has essential roles in several cancers." (PMID 40076494, 2025). "The expression of CYP4X1 was compared and analyzed using IHC staining of normal colon tissues (adjacent to cancer) and CRC tissues obtained from 243 patients with CRC." (PMID 40076494, 2025). "The aim of this study is to investigate the functional role of CYP4X1 expression in cancer, both in vitro and in vivo, and to correlate CYP4X1 expression with clinical parameters in cancer patients." (PMID 40076494, 2025). "CYP4X1, a member of the cytochromes P450 family, oxidatively metabolizes a wide range of physiological substrates and plays a potential role in the body in response to cancer chemotherapy." (PMID 34195087, 2021). "Thus, human CYP4X1 is a potential drug target for cancer therapy." (PMID 40076494, 2025). "Therefore, CYP4X1 might play a role in response to cancer chemotherapy through physiological processes." (PMID 33802237, 2021). "Therefore, targeting CYP4X1 may be a novel treatment strategy for carcinoma." (PMID 38556542, 2024).
CYP4X1 also shares sentences with these, for which no sentence is quoted: cervical cancer (1 paper); cervical squamous cell carcinoma (1); endocervical adenocarcinoma (1); endometrial carcinoma (1); esophageal carcinoma (1); glioblastoma multiforme (1); head and neck squamous cell carcinoma (1); kidney cancer (1); Obesity (1); rectal adenocarcinoma (1); thymoma (1); thyroid carcinoma (1).